RNU6-369P (RNA, U6 small nuclear 369, pseudogene)
Gene: Small nuclear RNA gene on chromosome 1 (44,390,722 to 44,390,823, forward strand). Ensembl gene ENSG00000199385.
Homologues: Orthologues: chimpanzee U6 (98% identical), macaque U6 (95% identical), dog U6 (81% identical), guinea pig U6 (81% identical), pig U6 (74% identical), rabbit U6 (60% identical). Paralogues in human: RNU6-11P (88% identical), RNU6-37P (88% identical), RNU6-480P (88% identical), RNU6-1103P (87% identical), RNU6-940P (87% identical), RNU6-961P (87% identical), RNU6-1 (86% identical), RNU6-15P (86% identical), RNU6-16P (86% identical), RNU6-188P (86% identical), RNU6-2 (86% identical), RNU6-21P (86% identical), and 1285 more.